LRRC75A (leucine rich repeat containing 75A)
Synonyms: C17orf76; FAM211A; FLJ35696
Tractability: No criterion of Open Targets' tractability assessment is met for any kind of drug.
Gene: Protein-coding gene on chromosome 17 (16,441,577 to 16,492,237, reverse strand). Ensembl gene ENSG00000181350.
Subcellular location (Human Protein Atlas): Nucleoplasm; Cytosol; Nucleoli
Gene Ontology:
Molecular function: ubiquitin-like ligase-substrate adaptor activity
Biological process: proteasome-mediated ubiquitin-dependent protein catabolic process
Cellular component: Cul2-RING ubiquitin ligase complex; cytoplasm
Genetic constraint (gnomAD): Loss-of-function variants: 12 observed, 20.65 expected, observed/expected ratio (o/e) 0.58, 90% interval 0.37 to 0.94. The upper end of that interval is the gene's LOEUF score, 0.94, which puts it in group 3 of 6, group 1 being the genes least tolerant of losing a copy. Missense variants: 410 observed, 420.71 expected, observed/expected ratio (o/e) 0.97, 90% interval 0.9 to 1.06. Synonymous variants: 223 observed, 187.42 expected, observed/expected ratio (o/e) 1.19, 90% interval 1.07 to 1.33.
Homologues: Orthologues: chimpanzee LRRC75A (99% identical), macaque LRRC75A (99% identical), pig LRRC75A (94% identical), mouse Lrrc75a (92% identical), rat Lrrc75a (92% identical), rabbit LRRC75A (92% identical), guinea pig LRRC75A (75% identical), tropical clawed frog lrrc75a (65% identical), zebrafish lrrc75a (64% identical), dog LRRC75A (60% identical).
Diseases named in the same sentence as LRRC75A in open-access papers:
LRRC75A is named in the same sentence as 6 diseases in open-access papers, as found by Europe PMC text mining. Sharing a sentence is not in itself a finding about the gene and the disease. The quoted sentences say what the papers report.
tumor (2 papers, 2021 to 2025). "Importantly, our findings were independently validated in a recent study of advanced ccRCC patients treated with cabozantinib, which demonstrated that higher LRRC75A expression was significantly associated with decreased tumor response and less robust reduction of VEGF expression." (PMID 40352330, 2025).
LRRC75A also shares sentences with these, for which no sentence is quoted: cancer (1 paper); cervical cancer (1); metastatic tumor (1); prostate carcinoma (1); Sepsis (1).